SATB1 (SATB homeobox 1)
Diseases named in the same sentence as SATB1 in open-access papers (continued):
Sharing a sentence is not in itself a finding about the gene and the disease.
tumor (continued). "Additionally, SATB1 expression level correlated with the grade of the tumour, its invasion depth, the TNM stage and the presence of lymph node metastasis." (PMID 31450715, 2019). "The role of SATB1 is dependent on the type of tumor and other potential factors." (PMID 31737131, 2019). "Additionally, SATB1′s expression levels correlated with the Gleason score of the tumours, the presence of bone metastasis and the expression of the EMT markers." (PMID 31450715, 2019). "To further test if SATB1 knockdown could promote AML progression in vivo, we compared the tumor size and weight in HL-60 SATB1-shRNA1 cells treated mice and the CTR mice." (PMID 31130823, 2019). "Moreover, ISH and IHC were performed to detect the expression of LINC01016, miR-302a-3p/miR-3130-3p, NFYA, and SATB1 in xenograft tumor tissues formed by Ishikawa cells." (PMID 29467441, 2018). "To investigate whether SATB-1 played a role in tumor formation in vivo, we performed a subcutaneous injection of SW1990 cells with stable SATB-1 knockdown (SATB-1#sh1) or mock-transfected cells (sh-NC) into the bilateral hind legs of athymic nude mice." (PMID 30337520, 2018). "In addition, SATB1 expression is also significantly correlated with poor tumor differentiation (OR: 1.76, 1.05–2.94)." (PMID 28430598, 2017). "Rather than using stably transfected cells, which may well interfere with tumor xenograft formation, the SATB1 knockdown was performed in already established tumors." (PMID 28049521, 2017). "We conducted this meta-analysis to investigate whether the invasion and metastasis of GIN correlates with SATB1 levels in tumor tissues in Chinese patients." (PMID 28636989, 2017). "Since SATB1 was first found to promote tumor growth and metastasis of breast malignancies in 2008, research has shown that SATB1 may influence tumor prognosis in multiple tumors." (PMID 28636989, 2017). "We also found that the detection of SATB1 expression in tumor tissues obtained through endoscopic biopsy may be used to evaluate the invasiveness of the tumor." (PMID 28636989, 2017). "Additionally, the observed absence of decreased SATB2 levels upon SATB1 knockdown in cells from another tumor entity further substantiates the notion of SATB2 reduction as a specific effect downstream of SATB1." (PMID 28049521, 2017). "On the functional side, initial data indicate that SATB1 may be involved in several tumor cell-relevant processes." (PMID 28049521, 2017). "In HCC, SATB1 is also reported to promote tumor metastasis and prevents apoptosis." (PMID 29050307, 2017). "Additionally, it was reported SATB1 also had opposite effect on cell proliferation between mouse embryonic fibroblasts (MEFs) and tumor cells." (PMID 27883059, 2016). "Therefore, the main objective of our study was to analyze and compare SATB1 gene expression in samples of tumor and unchanged colorectal tissues of CRC patients as well as in mucosal colon biopsies in a group of healthy subjects." (PMID 25874491, 2015). "In summary, SATB1 mRNA and SATB1 protein levels in tumor tissues differed significantly from those observed in the normal mucosa; thus, it may be assumed that altered SATB1 expression can precede the CRC-associated lesions." (PMID 25874491, 2015). "SATB1 expression positively correlates with tumor progression." (PMID 25590302, 2015). "In addition, the Ki67 proliferation index was comparable between BT-549-GFP and BT-549-sh-SATB1 tumors, despite a reduction in tumor size." (PMID 25586771, 2015). "Dysregulation of hypothetical SATB1 expression-controlling mechanism in colorectal tissue could lead to an aberrant SATB1 expression and result in global, tumor-promoting changes in affected cells." (PMID 25874491, 2015). "In this study, using TSMCL-DOX-shSATB1 system, both DOX and SATB1 shRNA vector could be guided to tumor site under magnetic filed guidance, and DOX was released in a hyperthermia triggered manner." (PMID 24675979, 2014).
tumor (continued). "Suppressing the expression of SATB1 by delivering siRNA or plasmid encoding specific interfering short harpin RNA (shRNA) against SATB1 could inhibit the proliferation and invasion, and promote apoptosis of tumor cells." (PMID 24675979, 2014). "Moreover, SATB1 expression predicted an improved response to adjuvant chemotherapy in both tumour types." (PMID 25323550, 2014). "The prognostic value of SATB1 is controversial in different tumor types, which may be due to tissue-dependent regulatory functions of SATB1." (PMID 25326863, 2014). "Furthermore, SATB1 mRNA and protein expression were higher in poorly differentiated tumor samples than in moderately differentiated tumor samples." (PMID 24971456, 2014). "SATB1 has been shown to promote tumor growth and metastasis by altering gene profiles." (PMID 24971456, 2014). "Similarly, transduction of SATB1into non-metastatic cells led to the invasion of tumors in mice, whereas silencing SATB1 lead cells to their normal phenotype and prevented tumor growth and metastasis." (PMID 23379909, 2013). "Importantly, SATB1565–574 -specific T cells were able to recognize and kill HLA-A*02+, SATB1-expressing tumor cells in an HLA-I-dependent manner." (PMID 23437226, 2013). "This suggests SATB1 expression in colorectal promotes tumor survival." (PMID 23326301, 2013). "We also show SATB1 cellular localization is correlated with tumor differentiation." (PMID 23326301, 2013). "Up-regulation of SATB1 in these types of cancers can promote tumor growth and metastasis." (PMID 23437226, 2013). "In contrast, SATB1-shRNA U251 xenograft tumor formation was significantly delayed." (PMID 22839214, 2012). "One, more simplistic, explanation for this observation could be that the beneficial prognostic value of SATB2, being expressed in the majority of CRC overrules the potential tumour-promoting effects of SATB1." (PMID 22935204, 2012). "We examined whether the maintenance of the aggressive phenotype in MCF10A-derived tumor cells requires sustained SATB1 expression." (PMID 23251624, 2012). "SATB1 recently demonstrated to be necessary for Xist RNA–dependent silencing in tumor T cells." (PMID 22606223, 2012). "Immunohistochemical expression of SATB1 and beta-catenin was assessed in tissue microarrays with tumours from 529 incident CRC cases in the prospective population-based Malmö Diet and Cancer Study, previously analysed for SATB2 expression and MSI screening status." (PMID 22935204, 2012). "Moreover, SATB1 is not only expressed in tumour cells, but also in stromal lymphocytes, and, importantly, the prognostic impact was evident even at low levels of expression, not least in the subgroup of SATB2 negative tumours." (PMID 22935204, 2012). "Similarly, the introduction of SATB1 into non-metastatic cells led to the induction of invasive tumors in mice; whereas SATB1 silencing returned cells to their normal phenotype and prevented metastasis and tumor growth." (PMID 19642980, 2009). "Notably, we report a significant decrease in the protein levels of key components of this pathway, including β-catenin, as well as a global regulator SATB1, following statin treatment suggesting that statin indeed mediates a tumor-suppressive phenotype by targeting aberrant Wnt signaling." (PMID 40689929, 2025). "Moreover, SATB1 has been implicated in promoting EMT, a critical process in tumor metastasis." (PMID 40071088, 2025). "Notably, SATB1 has been shown to repress PD-1 expression in tumor-reactive T cells." (PMID 40890836, 2025). "Additionally, SATB1’s involvement in regulatory networks that affect tumor microenvironment and immune cell interactions might contribute to its association with better outcomes in HL." (PMID 39195213, 2024). "Additionally, SATB1 may promote apoptosis in RS cells, thereby reducing the overall tumor burden and improving patient outcomes." (PMID 39195213, 2024).
tumor (continued). "Therefore, we postulate that SATB1 overexpression could enhance the immune system’s recognition of RS cells, leading to more effective immune-mediated destruction of the tumor." (PMID 39195213, 2024). "Moreover, the fact that HER ligands are not only expressed in tumor cells, but also in adjacent tumor stroma cells, indicates that effects obtained in ‘pure’ tumor cell models (even 3-D) may rather underestimate therapeutic efficacies of SATB1 inhibition." (PMID 32451408, 2020). "Furthermore, downregulation of SATB-1 inhibited tumor growth in mouse xenograft models." (PMID 30337520, 2018). "Therefore, we first analyzed SATB1 mRNA levels of ten different primary tumor samples." (PMID 28049521, 2017). "Following the subcutaneous implantation of 1×103 and 1×104 BT-549 cells, SATB1 depletion in the cells significantly reduced the success of engraftments, while subsequent to the subcutaneous implantation of 1×106 BT-549 cells, SATB1 knockdown significantly reduced tumor size after 21 days." (PMID 25586771, 2015). "Altogether, the reports suggest that SATB1 can be expressed in a tissue-typical manner, and prognostic value of SATB1 may be cancer-type specific; however, contradictory results could be observed even in the same tumor type." (PMID 25874491, 2015). "Spleen tumor weight increase caused by SATB1 expression was non-significant." (PMID 24971456, 2014). "In tumor cells with high levels of SATB1, genes that promote tumor progression and metastasis were up-regulated, whereas genes that inhibit tumor metastasis were repressed; while silencing of SATB1 greatly reduced the invasive and metastatic capacity of cancer cells." (PMID 23437226, 2013). "Special AT-rich sequence binding protein 1 (SATB1) is highly expressed in many types of human cancers as part of their neoplastic phenotype, and up-regulation of SATB1 expression is essential for tumor survival and metastasis, thus this protein may serve as a rational target for cancer vaccines." (PMID 23437226, 2013). "SATB1 has recently attracted considerable attention due to its high expression in tumor tissues of a variety of malignancies, which suggest a crucial role in promoting tumor growth, invasion and metastasis, and may also have a potential value of being a candidate for cancer therapy." (PMID 22839214, 2012). "Furthermore, the tumor growth of U251 cells expressing SATB1 shRNA were inhibited in vivo, and immunohistochemical analyses of tumor sections revealed a decreased vessel density in the animals where shRNA against SATB1 were expressed." (PMID 22839214, 2012). "Here, we further demonstrated that statins effectively reverse the expression patterns of SATB1 and SATB2 in both 2D cell cultures and 3D spheroid model systems, leading to a reduction in tumor burden in in vivo experiments." (PMID 40689929, 2025). "Downregulation of Wnt/β-catenin signaling and subsequent modulation of chromatin organizers SATB1 (oncogenic) and SATB2 (tumor suppressor), leading to reversal of epithelial-mesenchymal transition (EMT)." (PMID 41170235, 2025). "Correlation of expression of SATB1 and SATB2 across different grades and stages of tumor samples towards understanding CRC progression." (PMID 40177244, 2025). "Special AT-Rich Sequence Binding Protein 1 (SATB1) is a critical genome organizer that reprograms chromatin structure and broadly regulates transcriptional profiles to promote tumor cell proliferation and metastasis." (PMID 41372119, 2025). "Specifically, SATB1 showed a significant correlation with SLUG in SCC and Twist1 in AC, indicating its role in driving tumor progression via EMT in both subtypes." (PMID 40071088, 2025). "Evaluate expression and localization of SATB1 and SATB2 across paired human colon/rectum and tumor samples." (PMID 40177244, 2025).
tumor (continued). "Specifically, PIWIL4, SATB1, GSE1, NCOR1, SAP30L, ATM, and BMI1 were significantly downregulated in tumor tissues relative to normal controls, while BUB1, CHEK1, MASTL, DNAJC2, UBE2D1, and SSRP1 showed pronounced upregulation." (PMID 41208974, 2025). "SDF-1-mediated upregulation of SATB-1 expression in tumor cells contributed to the maintenance of CAF properties, forming a reciprocal feedback loop involving the SDF-1/SATB-1 pathway." (PMID 35326670, 2022). "Knockdown of Prnp resulted in loss of SATB1 expression and reduction of metastatic capacity in CRC with Fyn and specificity protein 1(SP1) being involved in this process, indicating that PrPC may promote tumor metastasis via upregulating the PrPC-Fyn-SP1-SATB1 axis." (PMID 34595121, 2021). "Higher PR and HER2 expression in the tumor tissue, CD8+ and CD8+SATB1+ cell densities in the stroma and tumor tissue, ER and PR entropy, contrast, dissimilarity and PR AshD are associated with higher OS probabilities." (PMID 32612954, 2020). "Our study was designed to comprehensively and systematically analyze the cellular and molecular role of SATB1 in HNSCC by using transient RNAi-mediated knockdown in vitro and in tumor xenograft mouse models in vivo." (PMID 32451408, 2020). "SATB1 has been found to be upregulated in various solid tumors including HNSCC, and its role in cancer progression has thus been studied in different tumor entities in great detail (15; see16,17 for review)." (PMID 32451408, 2020). "In this paper, we comprehensively analyze cellular and molecular effects of SATB1 in a large set of primary cell lines from primary HNSCC or metastases, using RNAi-mediated knockdown in vitro and, therapeutically, in tumor xenograft mouse models in vivo." (PMID 32451408, 2020). "The sustained expression of PD1 is linked to chronic infections and cancer due to CD8 cell exhaustion, hence SATB1 likely controls both PD1 expression and anti-tumor T cell responses." (PMID 33356851, 2020). "This also included the chromatin-organizer protein SATB1, as an established regulator of HER expression in other tumor entities." (PMID 33374770, 2020). "On the other hand, the density of CD8+ cells in tumor compartment revealed positive prognostic value (HR = 0.23, p = 0.00047); however, it was outperformed by CD8+SATB1+ in the multivariate prognostic model (HR = 0.30, p = 0.0035)." (PMID 32612954, 2020). "Collectively, these results support the notion that the role of SATB1 in regulating the expression of different HER receptors strongly depends on the cellular and/or tumor context." (PMID 33374770, 2020). "Surgically excised tumor samples from 101 female patients with hormone receptor-positive breast cancer (HRBC) were stained for ER, PR, HER2, Ki67, SATB1, CD8, and scanned at 20x." (PMID 32612954, 2020). "SATB1, a homologous gene of SATB2, has been reported to act as a critical regulator of tumor immune response." (PMID 31492160, 2019). "Satb1 was also shown to be important for regulation of PD1 expression and T cell anti-tumor activity." (PMID 30420856, 2018). "We also analyzed SATB1 expression and its relation to the clinicopathological characteristics such as TNM stage, lymph node involement and tumor differentiation." (PMID 28430598, 2017). "Many potential targets of miR-7 were reported to participate in some important signalling of tumor progression, such as targets EGFR, IRS-1, PAK-1, RAF-1, SATB1, and so on." (PMID 28239300, 2017). "Our results indicated that SATB1 overexpression was accompanied by progression of GIN and that the expression level differed according to the tumor type." (PMID 28636989, 2017). "The expression of SATB1 mRNA in healthy colon mucosa and unchanged tissue of CRC patients was significantly elevated when compared to the tumor tissues (1.00 ± 0.01 and 0.53 ± 0.01 vs. 0.25 ± 0.01, respectively; P < 0.0001)." (PMID 25874491, 2015).
tumor (continued). "Apart from considerations in the adjuvant situation, SATB1 could also prove to be a useful biomarker for identification of patients with borderline resectable tumours who will respond well to neoadjuvant chemotherapy, thus increasing the number of resectable tumours." (PMID 25323550, 2014). "Kaplan-Meier analysis revealed that SATB1 expression was prognostic for OS and RFS in the PB-group of tumours." (PMID 25323550, 2014). "The interaction between SATB1 and adjuvant chemotherapy in relation to RFS was significant also when considering positivity in primary tumours only, p(interaction) = 0.032." (PMID 25323550, 2014). "The expression level of SATB1 mRNA and protein was determined in primary CRC tumor and matched non-tumor mucosa specimens." (PMID 24971456, 2014). "There was a significant interaction between SATB1 and adjuvant chemotherapy in relation to RFS in I-type tumours, p(interaction) = 0.021." (PMID 25323550, 2014). "More specifically, we focused on a select number of SATB1 target genes that are known to participate in tumorigenesis and metastasis (e.g. tumor/metastasis suppressors BRMS1, Kiss1, Claudin-1; tumor/metastasis promoters c-Abl, MMP3, ErbB2 and Snail)." (PMID 24260116, 2013). "We have identified a novel HLA-A*02-restricted SATB1-derived peptide epitope recognized by CD8+ T cells, which, in turn, recognizes and kills HLA-A*02+ SATB1+ tumor cells." (PMID 23437226, 2013). "The tumor cell lines showed different absorbance abilities: untransfected U251 cells, 0.6020.007; control-shRNA-GFP U251 cells, 0.5930.016; SATB1-shRNA U251 cells, 0.2620.014." (PMID 22839214, 2012). "This pattern suggests inverse relation between SATB1 and HIF-1α co-expression and the co-expression of AR, ER, and BCL2 in the subgroup of HR-positive tumours." (PMID 22424533, 2012). "Additionally, fluvastatin significantly inhibits tumor progression in NSCLC H292 cells, potentially by downregulating SATB1 via the Wnt/β-catenin pathway." (PMID 40071088, 2025). "We hypothesized that SATB1 overexpression could reprogram CAR-T cell epigenetics to resist exhaustion and enhance anti-tumor efficacy in HCC." (PMID 41372119, 2025). "SATB1 regulates gene expression by mediating histone modifications as it recruits histone-modifying enzymes on promoters of oncogenes and also recruits HDAC1 on promoters of tumor suppressor genes." (PMID 40071088, 2025). "Moreover, after co-culture with GPC3+ Huh7 cells for 3 days, SATB1-CAR-T cells exhibited reduced apoptosis levels, indicating improved resistance to tumor-induced stress." (PMID 41372119, 2025). "The unique expression patterns of SATB1 and SATB2 proteins in the tumor samples further support our hypothesis regarding statin-mediated modulation of the canonical Wnt pathway." (PMID 40689929, 2025). "Subsequent studies demonstrated that SATB1-overexpressing CAR-T cells exhibited improved resistance to exhaustion and superior immunotherapeutic efficacy in vivo, leading to accelerated tumor eradication and prolonged survival of tumor-bearing mice." (PMID 41372119, 2025). "Furthermore, SATB1 influences gene expression in HCC cells, regulating over 300 genes involved in tumor growth and metastasis." (PMID 40071088, 2025). "SATB1, a global chromatin organizer, is dysregulated in human cutaneous TCL by promoting the expression of TH-2 cytokines (IL-5 and IL-9), which were appropriate for the tumor microenvironment." (PMID 39176397, 2024). "As a result, SATB1-deficient T cells failed to repress the elevation of inhibitory PD-1 upon TCR activation, limiting the function of tumor-reacting T cells." (PMID 35812421, 2022). "No significant results were obtained when SATB1 expression was evaluated in only one tissue core selected at random from each tumor (p = 0.068)." (PMID 34961766, 2021). "For SATB1, nuclear and cytoplasmic immunoreactivity occurred in epithelial tumor cells or normal epithelium of the prostate but not in stromal tissue cells." (PMID 34961766, 2021).